SIRT1 (sirtuin 1)
Diseases named in the same sentence as SIRT1 in open-access papers (continued):
Sharing a sentence is not in itself a finding about the gene and the disease.
oral cancer (continued). "In oral cancer, SIRT1 expression correlated with tumor repression and its downregulation at transcriptional level is linked to malignant transformation, invasion and metastasis." (PMID 32878301, 2020). "Deregulated SIRT1 expression was demonstrated previously in various human malignant diseases including oral cancer." (PMID 31931863, 2020). "In summary, our data show that SIRT1 inhibited the EMT process in oral cancer by deacetylating Smad4 and repressing expression of MMP7." (PMID 25424420, 2014). "Despite its implied involvement in a variety of physiological processes, the regulatory role of SIRT1 in oral cancer metastasis is poorly understood." (PMID 25424420, 2014). "SIRT1 shows potential for serving as a predictor and biomarker for metastasis, and up-regulation of SIRT1 is a potentially useful therapeutic strategy for inhibiting the metastasis of oral cancers." (PMID 25424420, 2014). "In contrast, SIRT1 silencing in oral cancer cells resulted in a significant induction of MMP7 secretion." (PMID 25424420, 2014). "SIRT1 overexpression repressed the EMT process in oral cancers and blocked migration of OSCC cells in vitro." (PMID 25424420, 2014). "Despite evidence for SIRT1 involvement in a variety of cell regulatory and physiological processes, the role of SIRT1 in regulating oral cancer metastasis and EMT remains enigmatic." (PMID 25424420, 2014). "In this study, we investigated the involvement of SIRT1 in EMT as it occurs in oral cancer metastasis." (PMID 25424420, 2014). "In contrast, an SIRT1 antagonist (sirtinol) was completely ineffective in suppressing cell migration, and greatly increased oral cancer cell metastasis in vitro." (PMID 25424420, 2014). "In this setting, SIRT1 knockdown hinders apoptosis activation in GA-primed oral cancer cells." (PMID 37949849, 2023). "In the present study, we have focused on unrevealing the intricate role of SIRT1 as a tumor suppressor gene in oral cancer during chemotherapy and the molecular aspects that SIRT1 regulates during therapeutic intervention with special insight into mitochondrial dynamics." (PMID 37949849, 2023). "Similarly, SIRT1 overexpression in the CDDP resistance oral cancer-derived polyploid giant cancer cells (PGCCs) re-sensitizes the cells to apoptosis." (PMID 37949849, 2023). "Interestingly, the expression of SIRT1 was found to be downregulated across oral cancer cell lines with minimal expression in Cal33 and FaDu cells." (PMID 37949849, 2023). "Moreover, through increasing E-cadherin expression, SIRT1 is able to promote epithelial integrity in oral cancer cells, thereby suppressing invasion and metastasis." (PMID 36815979, 2023). "Previously, it has been demonstrated that SIRT1-activating drugs have immense potential as anticancer drugs, hence targeting SIRT1 might give a novel therapeutic avenue for treating oral cancer." (PMID 37949849, 2023). "Hence, we primed the oral cancer cells with low doses of GA for 3 weeks and checked the SIRT1 activity." (PMID 37949849, 2023). "In our initial observation, we found reduced SIRT1 expression in the oral cancer-derived PGCCs." (PMID 37949849, 2023). "SIRT1 overexpression re-sensitizes oral cancer-derived PGCCs to CDDP-induced apoptosis." (PMID 37949849, 2023). "However, further investigation is warranted to delineate the mechanistic involvement of SIRT1 as a directive target for mitochondrial dynamics with the commendable therapeutic intervention against oral cancer." (PMID 37949849, 2023). "Moreover, crucial role of SIRT1 activation in sensitizing the cancer cells to apoptosis via inhibition of mitochondrial hyperfusion was deciphered in CDDP-resistant oral cancer cells." (PMID 37949849, 2023). "The influence of SIRT1 on epithelial e-cadherin activity is indicated as a potential mechanism, which allows the preservation of the integrity of the epithelium and preventing of metastases in oral cancer." (PMID 34685718, 2021).
oral cancer (continued). "From these observations, we hypothesize that decreased SIRT1 expression may occur in oral cancer induced by BQ chewing habit." (PMID 31931863, 2020). "However, despite evidence for SIRT1 involvement in a variety of cell regulatory and physiological processes, the role of SIRT1 in regulating oral cancer progression and metastasis is poorly investigated." (PMID 32878301, 2020). "Moreover, in vitro studies on Cal 27 cells and xenograft mouse model support the potential of SIRT1 as tumor suppressor in oral cancer and provide the rationale for the use SIRT1 activators from dietary source in the setting of new prevention strategies." (PMID 32878301, 2020). "Our results suggest that DNA hypermethylation of SIRT1 is involved in the occurrence of oral cancer in BQ chewing patients and that hypermethylation in the oral mucosa of BQ chewers could be a predictive marker for the occurrence of malignant transformation." (PMID 31931863, 2020). "Our findings suggest the SIRT1/Smad4/MMP7 pathway as a target for oral cancer driven by EMT." (PMID 25424420, 2014). "In contrast, knockdown of SIRT1 in oral cancer cells enhanced EMT and cancer metastasis in vitro." (PMID 25424420, 2014). "Finally, we show that SIRT1 overexpression reduced the invasiveness and metastasis of oral cancer cells in immunodeficient mice." (PMID 25424420, 2014). "Taken together, these data suggest that SIRT1 may prevent oral cancer metastasis by blocking the EMT process." (PMID 25424420, 2014). "Recently, the enzyme SIRT1 has been implicated in a variety of physiological processes; however, its role in regulating oral cancer metastasis and EMT is not fully elucidated." (PMID 25424420, 2014). "Finally, we explored the potential clinical relevance of tNOX and SIRT1 protein in oral cancer." (PMID 38567911, 2024). "Additionally, SIRT1 suppresses mesenchymal makers N-cadherin and vimentin expression and downregulates migration and invasion genes, such as csk2a2, fra1, actb, and slug, preventing oral cancer." (PMID 36815979, 2023). "However, one study showed that capsaicin inhibits SIRT1 to enhance the acetylation of unc-51-like autophagy activating kinase 1 (ULK1) to trigger autophagy in oral cancer cells, which suggests that SIRT1 may inhibit autophagy in oral cancer cells." (PMID 36815979, 2023). "However, the physiological relevance of SIRT1 in BQ-related oral cancer remains unexplored." (PMID 31931863, 2020). "Since the downregulated expression of SIRT1 has been attributed to DNA hypermethylation, we hypothesize that DNA hypermethylation of SIRT1 may be observed followed by its transcriptional downregulated expression in BQ chewing oral cancer patients." (PMID 31931863, 2020). "Therefore, we conducted Boyden Chamber assays to determine whether the deacetylase activity of SIRT1 would suppress the migration and invasion of oral cancer cells." (PMID 25424420, 2014). "SIRT1 (NAD-dependent protein deacetylase sirtuin-1), a class III histone deacetylase acting as a tumor suppressor gene, is downregulated in oral cancer cells." (PMID 37949849, 2023). "At the nucleus, SIRT1 attaches to the promoter region of TGF- β, inhibits CBP/p300-mediated acetylation and leads to transcriptional suppression of TGF- β-mediated oral cancer progression." (PMID 36815979, 2023). "A related compound, cudraflavone B, induces apoptosis in human oral cancer cells by modulating mitogen-activated protein kinase (MAPK), sirtuin-1 and Nuclear factor-κB (NFκB) pathways." (PMID 28107519, 2017). "We found that compared with normal human oral keratinocytes (HOKs), SIRT1 was underexpressed in OSCC cells, and also in oral cancer tissues obtained from 14 of 21 OSCC patients compared with expression in their matched normal tissues." (PMID 25424420, 2014). "Thus, SIRT1 activation appears to be tightly correlated with cell migration and invasion ability, and SIRT1 might be an important regulator of migration and invasion in oral cancer cells." (PMID 25424420, 2014).
oral cancer (continued). "Sirtuins (SIRT1-7) are a family of NAD-dependent deacetylases, which play an important role in regulating cancer tumorigenesis; however, their role in oral cancer has been controversial." (PMID 23800187, 2013). "SIRT1, which belongs to class III of the HDAC super-family, has the unique feature of being NAD+-dependent; it contributes to inflammatory oral diseases and oral cancer by modulating many transcription factors and antioxidant enzymes." (PMID 38567911, 2024). "Moreover, SIRT1 activation potently induces cell death by apoptosis in oral cancer and cisplatin (CDDP)-resistance oral cancer cells via inhibiting mitochondrial hyperfusion." (PMID 37949849, 2023). "SIRT1 hypermethylation has been observed in OSCC cells and the tissues of AN users; thus, SIRT1 hypermethylation may be a biomarker of oral cancer." (PMID 37190117, 2023). "In addition, Cud B inhibited cancer cells growth and induced mitochondrial-dependent apoptosis in human oral cancer cells through regulation of MAPK, NFκB, and SIRT1 signaling." (PMID 28107519, 2017). "Thus, SIRT1 participates in regulation of MMP7 activity and expression by deacetylating K37 of Smad4, and repressing the effect of TGF-β signaling in oral cancer." (PMID 25424420, 2014). "To evaluate the role of SIRT1 in regulating oral cancer metastasis and EMT, we first investigated whether SIRT1 expression in normal primary human oral keratinocytes (HOKs) differed from that in OSCC cells." (PMID 25424420, 2014). "Our results showed that SIRT1 overexpression reduced oral cancer cell migration and metastasis, and these effects were largely independent of any general effects of SIRT1 on oral cancer growth and survival." (PMID 25424420, 2014). "MMP7 expression has been significantly correlated with oral cancer metastasis and EMT, which suggests that the SIRT1 overexpression might affect MMP7 expression in OSCCs." (PMID 25424420, 2014). "Similar to SIRT1, SIRT3 may function as either an oncogene or suppressor in oral cancer." (PMID 36815979, 2023). "However, the methylation and transcription status of SIRT1 in patients with BQ chewing-related oral cancer has not been investigated." (PMID 31931863, 2020). "Considering that tNOX not only supports but also exerts functions independent of SIRT1, the tNOX- and SIRT1-inhibiting function of 4-dmH, thus, results in the different biological outcomes from the SIRT1-binding heliomycin, as evidenced by the results of in vitro and in vivo studies of oral cancer." (PMID 38567911, 2024).
oral squamous cell carcinoma (16 papers, 2014 to 2024). "In oral squamous cell carcinoma cells, overexpression of sirtuin-1 results in a decrease in acetylated SMAD4 and an inhibition of TGF-β–mediated cell migration." (PMID 35203583, 2022). "On the other hand, it has been demonstrated that SIRT1 is involved in the acquisition of CDDP-resistance in oral squamous cell carcinoma (OSCC) cells." (PMID 34445277, 2021). "The effect of SIRT1 in EMT phenotype though SMAD4 deacetylation has also been reported in oral squamous cell carcinoma." (PMID 32340156, 2020). "We found that increased levels of SIRT1 in oral squamous cell carcinoma tissue contributing to decreased Smad4 acetylation and repressed MMP7 activity." (PMID 25424420, 2014). "RNA interference was used to knockdown either SIRT1 or Smad4 expression in oral squamous cell carcinoma (OSCC) cell lines." (PMID 25424420, 2014). "We also found that activation of SIRT1 in oral squamous cell carcinoma resulted in decreased cell migration and invasion." (PMID 25424420, 2014). "In this study, we demonstrated that SIRT1 suppresses the EMT process in oral squamous cell carcinoma cells by deacetylating Smad4 and repressing MMP7 expression." (PMID 25424420, 2014). "However, in oral squamous cell carcinoma, SIRT1 acts as a potential tumor suppressor." (PMID 38044396, 2024). "Previous studies have revealed that SIRT1 promotes the EMT and metastasis in chondrosarcoma, osteosarcoma, oral squamous cell carcinoma, hepatocellular carcinoma, pancreatic cancer and colorectal cancer." (PMID 29374154, 2018). "We examined the methylation status of SIRT1 in paraffin-embedded tissue samples of oral squamous cell carcinoma (OSCC) obtained from BQ chewing and non-chewing patients and in tissue samples from healthy control subjects." (PMID 31931863, 2020). "In the present study, we analyzed the methylation status of SIRT1 in paraffin-embedded tissue samples of oral squamous cell carcinoma (OSCC) obtained from BQ chewing and non-chewing patients and in tissues samples from healthy control subjects." (PMID 31931863, 2020).
polycystic ovary syndrome (16 papers, 2016 to 2026). A disorder that manifests as multiple cysts on the ovaries. "For example, polycystic ovarian syndrome is associated with decreased expression of SIRT1." (PMID 27886120, 2016). "Inhibition of SIRT1 reduces the ovarian reserve and participates in the development and progression of polycystic ovary syndrome (PCOS) and premature ovarian failure (POF)." (PMID 39232832, 2024). "We aim to investigate the potential therapeutic effects of combined therapy of resveratrol and metformin on polycystic ovaries via SIRT1 and AMPK activation." (PMID 29958542, 2018). "For example, the pharmacological up-regulation of SIRT1 suppressed the manifestations of polycystic ovarian syndrome in rats." (PMID 27886120, 2016). "Studies have shown that combination therapy with metformin and empagliflozin can significantly improve ovarian function in women with polycystic ovary syndrome (PCOS) by upregulating the expression of AMPKα and sirtuin 1 (SIRT1)." (PMID 39272875, 2024). "For various ovarian endocrine disorders, such as polycystic ovary syndrome (PCOS), metformin, melatonin, and resveratrol have been used as targeted therapies, the underlying mechanisms of which are closely related to the expression of SIRT1, thus achieving significant therapeutic effects." (PMID 36975503, 2023). "Melatonin can enhance PDK1/Akt or PINK1/Parkin signaling in granulosa cells in polycystic ovary syndrome (PCOS) patients to alter the expression levels of the SIRT1 gene, thereby regulating mitochondrial function." (PMID 37239427, 2023). "These plant compounds, which have been shown to be able to upregulate SIRT1 expression in polycystic ovaries, also lowered testosterone levels and increased the estradiol blood concentration in laboratory animals treated with letrozole to induce polycystic ovary syndrome." (PMID 37762053, 2023). "In an animal model of polycystic ovary syndrome (PCOS), fisetin and quercetin induced SIRT1 expression as effectively as metformin." (PMID 37762053, 2023).
Ureteral obstruction (16 papers, 2016 to 2025). Obstruction of the flow of urine through the ureter. "Sirt1 activation by either resveratrol or Sirt1 agonist (SRT3025) decreases unilateral ureteral obstruction (UUO), 5/6 nephrectomy-induced renal inflammation, and ECM accumulation by Smad3 acetylation." (PMID 35563783, 2022). "In our study, we found that ablation of Sirt1 in renal interstitial cells resulted in more severe renal damage and fibrosis in unilateral ureteral obstruction (UUO) model mice." (PMID 33758176, 2021). "Tubulointerstitial fibrosis and decreased Sirt1 expression was found in the kidney of unilateral ureteral obstruction rats." (PMID 30714469, 2019). "Thus,honokiol – a SIRT3 activator – counteracts kidney fibrosis inmice with unilateral ureteral obstruction.Similarly, activation of both SIRT1 and SIRT3 by resveratrolattenuates cardiac fibrosis in mice by inhibiting the TGF-β/Smad3 pathway." (PMID 38680178, 2024). "In experimental models of acute and chronic kidney injury, chronic systemic SIRT1 activation with resveratrol significantly improves adriamycin-induced, subtotal nephrectomy-induced and unilateral ureteral obstruction-induced renal dysfunction through the anti-inflammatory effects." (PMID 33513830, 2021). "The decreased level of SIRT1 is associated with an increased level of apoptosis after unilateral ureteral obstruction(UUO), and a SIRT1 activator reduced this kind of damage." (PMID 34434166, 2021). "Activation of sirtuin 1 (Sirt1) attenuates unilateral ureteral obstruction (UUO)-induced inflammation and fibrosis, suggesting that Sirt1 may prevent tubulointerstitial fibrosis." (PMID 27659793, 2016).
experimental autoimmune encephalomyelitis (15 papers, 2017 to 2024). An autoimmune demyelinating disease of the central nervous system that is produced experimentally in animals by the injection of homogenized brain or spinal cord in Freund's adjuvant. "Using the AAV2 vector as a delivery system, we showed that SIRT1 overexpression in multiple cell types in the retina driven by a ubiquitous promoter induced a small reduction in RGC loss in a model of experimental autoimmune encephalomyelitis (EAE)." (PMID 35740955, 2022). "SIRT1-null mice not only develop systemic lupus erythematous-like symptoms spontaneously, but also are more susceptible to induced experimental autoimmune encephalomyelitis (EAE)." (PMID 30622543, 2018). "Mice with astrocyte-specific Sirt1 knockout (Sirt1–/–) had suppressed progression of experimental autoimmune encephalomyelitis (EAE), an animal model of CNS inflammatory demyelinating disease." (PMID 36136587, 2022). "T cell-specific deletion of SIRT1 and SIRT1-specific inhibitors suppress the Th17 program and are protective in mouse models of experimental autoimmune encephalomyelitis (EAE)." (PMID 32709897, 2020). "A previous study has indicated that overexpression of SIRT1 protein in neurons protected against experimental autoimmune encephalomyelitis (EAE) by activating multiple SIRT1 targets." (PMID 29561961, 2018). "Overexpression of SIRT1 protein in neurons protects against experimental autoimmune encephalomyelitis through activation of multiple SIRT1 targets." (PMID 29081884, 2017). "In experimental autoimmune encephalomyelitis (EAE) model of MS in young mice, OPCs exhibited cell-cycle arrest linked to an upregulation of sirtuin 1 (SIRT1) transcription, suggesting that failure of OPC proliferation may be due to CS." (PMID 32694983, 2020). "In experimental models of MS (i.e., experimental autoimmune encephalomyelitis—EAE), the activation of SIRT1 was shown to reduce neuronal injury in brain, spinal cord, and retinal ganglion cells, preventing subsequent neurological deficit." (PMID 39335541, 2024).